AQP1 (aquaporin 1 (Colton blood group))
Diseases named in the same sentence as AQP1 in open-access papers (continued):
Sharing a sentence is not in itself a finding about the gene and the disease.
breast cancer (continued). "The application of our study includes, but is not limited to, facilitating screening of the most appropriate breast cancer patients (who have a high AQP1 expression) for better anthracycline chemotherapy and improved prognosis purposes." (PMID 32814878, 2021). "After demonstrating the relationship between AQP1 and anthracycline chemotherapy, we intended to apply miRNAs to regulate the expression of AQP1, thereby regulating the sensitivity of breast cancer cells to anthracyclines." (PMID 32814878, 2021). "The expression pattern of AQP1 in breast cancer cells suggests a possible relation between its cytoplasm localization and its function in breast cancer development." (PMID 32814878, 2021). "Our present study showed, through the ubiquitin-proteasome system in AQP1 overexpressed breast cancer cells, the AQP1 overexpression inhibited the degradation of β-catenin, thus promoting β-catenin accumulation in the cytoplasm." (PMID 32814878, 2021). "The co-localization of AQP1 and β-catenin was confirmed in primary breast cancer cells by immunofluorescence analysis." (PMID 32814878, 2021). "Then we applied primary breast cancer cells from two patients and found that overexpression of miR-320a-3p reduced the expression of AQP1." (PMID 32814878, 2021). "The data showed that AQP1 expression was significantly negatively correlated with miR-320a-3p level in breast cancer, especially in the luminal subtype." (PMID 32814878, 2021). "Breast cancer tissues showed upregulation of AQP1, -3, and -5 at transcript and protein levels as compared to normal breast tissue, at levels dependent on cancer subtype and stage." (PMID 33499000, 2021). "AQP1 expression has been detected only in a subgroup of CK14-positive basal-like breast cancer (BLBC) cases." (PMID 32782435, 2020). "A few studies have reported the expression of AQPs in breast cancer, mainly AQP1, AQP3, and AQP5, that were found higher expressed in tumors than in normal adjacent tissues." (PMID 31379986, 2019). "We found that the MDA-MB-231 cell line expressed the highest level of AQP1 transcript of the four breast cancer cell lines tested." (PMID 31574930, 2019). "We assessed the effects of bac I and bac II on breast cancer cell migration, since AQP1 is known to be important in this process and these drugs target AQP1 function." (PMID 31574930, 2019). "Breast cancer is one of the tumors with increased microvessels and angiogenesis compared to its matched normal tissue and there is an increased AQP1 expression in the microvasculature of breast tumor." (PMID 30678106, 2019). "Several previous studies reported that high AQP1 expression was related to an unfavorable prognosis including cutaneous melanoma, pharyngeal carcinomas, urothelial carcinoma, and breast cancer." (PMID 29472315, 2018). "In line with previous studies, our studies demonstrated that overexpression of AQP1 in breast cancer cells induced an increased migration and invasion, which were also consistent with our present clinical findings." (PMID 26812884, 2016). "The results indicated that high cytoplasmic expression of AQP1 led to a worse prognosis in 275 cases of luminal breast cancer (including 60 luminal A cases and 215 luminal B cases)." (PMID 26812884, 2016). "41.9% (143/341) of IDC, 28.9% (13/45) of DCIS and 15.2% (5/33) of benign breast lesions showed high cytoplasmic expression of AQP1, indicating that cytoplasmic AQP1 probably be involved in breast cancer progression." (PMID 26812884, 2016). "Based on above results, we analyzed AQP1 cytoplasmic expression in 50 primary breast cancer tissues and their paired lymph node metastases." (PMID 26812884, 2016). "44% (22/50) primary breast cancer tissues showed high cytoplasmic AQP1 expression, while 68% (34/50) lymph node metastasis specimens exhibited high AQP1 cytoplasmic expression (P = 0.042)." (PMID 26812884, 2016).
breast cancer (continued). "Both results of BrdU and soft agar assays in our present study showed that overexpression of AQP1 promoted the proliferation of breast cancer cells, which were consistent with previous reports and our present clinical findings." (PMID 26812884, 2016). "Cytoplasmic expression of AQP1 increased with increasing histological grade and pTNM stage of breast cancer." (PMID 26812884, 2016). "In the following studies, the role of AQP1 in breast cancer development was validated by in vitro experiments." (PMID 26812884, 2016). "In order to explore the role of AQP1 in breast cancer prognosis, we analyzed 324 IDC patients with complete clinical follow-up." (PMID 26812884, 2016). "We have shown here for the first time that, as in melanoma and breast cancer, AQP1 also promotes cell migration in MM." (PMID 25821338, 2015). "AQP1 was mainly over-expressed in the cytoplasm of breast cancer cells and correlated with poor prognosis of patients with breast cancer as an independent prognostic factor." (PMID 25886458, 2015). "Based on these results the investigators suggested that AQP1 expression is a characteristic feature of aggressive basal-like breast carcinomas." (PMID 24338153, 2014). "The authors found that expression of AQP1 in blood vessels of human breast carcinoma tissues were significantly higher than controls, confirming the observations of several earlier studies." (PMID 24338153, 2014). "Aquaporin-1 (Aqp1) is proposed as a mediator of estrogen-induced angiogenesis in breast cancer and endometrial cancer." (PMID 23847593, 2013). "The current results agree with data from a study of AQP1 expression in glioblastoma and breast cancer transplanted into mouse brain." (PMID 12237771, 2002). "AQP1 promotes the migration and invasion of breast cancer cells." (PMID 41463012, 2025). "Moreover, it appears that AQP1 overexpression in breast cancer plays a role in chemotherapy sensitivity." (PMID 39857629, 2024). "Actually, breast cancer patients with high levels of AQP1 expression who received the anthracycline treatment had better clinical outcomes as compared with those with low levels of AQP1 expression." (PMID 39857629, 2024). "Inhibition of AQP1 in breast cancer increased sensitivity to anthracycline treatment." (PMID 39123442, 2024). "With no fine-tuning of our mammary tissue (GTEx) model, we see RNAPath is able to predict known marker genes, for example, PLIN1 in adipocytes (r score = 0.29, P-value = 2.27 × 10−19) or breast cancer related genes like AQP1 (r score = 0.32, P-value = 1.58 × 10−23)." (PMID 39003292, 2024). "AQP1 mRNA was upregulated after leptin treatment for 24 h in both breast cancer cells by RT-PCR." (PMID 38791252, 2024). "Our findings suggested a novel mechanism for AQP1-induced breast cancer local invasion." (PMID 36803413, 2023). "Our present study demonstrated AQP1 was a crucial target in breast cancer local invasion." (PMID 36803413, 2023). "Similarities in genetic and histological features between endometrial, epithelial ovarian, and breast cancers suggest AQP1 might have prognostic significance across multiple classes of hormone-sensitive cancers." (PMID 37760476, 2023). "Both in vivo assay and clinical analysis data confirmed that AQP1 could induce breast cancer progression by interacting with ANXA2 and Rab1b." (PMID 36803413, 2023). "We tested the effects of AQP1-overexpression on breast cancer biological function." (PMID 36803413, 2023). "Furthermore, AQP1 is associated with estrogen-induced angiogenesis in ER+ breast cancer, as estrogen activates the estrogen-response element (ERE) in the AQP1 promoter and promotes AQP1 expression." (PMID 38136293, 2023). "We used RNA-sequencing data to further explore how AQP1 modulated breast cancer local invasion." (PMID 36803413, 2023). "Further, AQP1 is involved in microvascular alteration during prostate tumour angiogenesis; and it promotes sensitivity of anthracycline chemotherapy in breast cancer." (PMID 36743211, 2023).
breast cancer (continued). "Here, we show that the cytoplasmic water channel protein AQP1, a crucial target in breast cancer local invasion, recruited ANXA2 from the cellular membrane to the Golgi apparatus, promoted Golgi apparatus extension, and induced breast cancer cell migration and invasion." (PMID 36803413, 2023). "Because bone is the most common site for breast cancer metastasis, targeting AQP1 with miR-495 could be therapeutically beneficial and reduce bone destruction in breast cancer patients." (PMID 36212456, 2022). "Previously, we reported that the membrane water channel protein AQP1 mainly localized in the cytoplasm of breast cancer cells and that the cytoplasmic expression of AQP1 could promote the malignant progression of breast cancer." (PMID 32814878, 2021). "For example, miR-3194-3p suppresses cell invasion and growth by targeting AQP1 in breast cancer." (PMID 34516362, 2021). "We showed that breast cancer patients with a high level of AQP1 expression who underwent the anthracycline treatment had a better clinical outcome relative to those with a low level of AQP1 expression." (PMID 32814878, 2021). "AQP1 upregulation in breast cancer, induced by estrogen and negatively regulated by microRNA-320, was correlated with prognoses of poor survival for breast cancer patients." (PMID 32679804, 2020). "Increasing evidence indicates that the Aquaporin1 (AQP1) aberrant expression may be related to a wide variety of human cancers, including breast cancer (BC)." (PMID 32903818, 2020). "Four genes AQP1, LFNG, RASSF2 and WWP2 were reported to be associated with breast cancer." (PMID 31640538, 2019). "Our recent study demonstrated that overexpression of AQP1 in tumor cells could promote proliferation and invasion ability and high cytoplasmic expression of AQP1 indicated worse outcome of breast cancer patients." (PMID 29245912, 2017). "In addition, both endogenous expression of AQP1 in primary breast cancer cells and exogenous overexpression of AQP1 in MDA-MB-231 cells were examined by immunofluorescence analyses." (PMID 26812884, 2016). "In conclusion, our study provided the first evidence that cytoplasmic expression of AQP1 promoted breast cancer progression and it could be a potential prognostic biomarker for breast cancer." (PMID 26812884, 2016). "Moreover, in line with our findings in clinic, cytoplasmic expression of AQP1 was further validated in both primary cultured breast cancer cells and AQP1 over-expressing cell lines, in which the functional importance of cytoplasmic AQP1 was confirmed in vitro." (PMID 26812884, 2016). "AQP1 has been proposed as a mediator of estrogen-induced angiogenesis in human breast cancer." (PMID 24338153, 2014). "Over-expression of AQP1 increases the metastatic potential of breast cancer cells." (PMID 23468877, 2013). "Finally, 3 of the 22 anti-AQP1 positive patients also had neoplasms (nephroma, non-Hodgkin lymphoma, or mammary cancer)." (PMID 24086369, 2013). "Thus, AQP1 mediates leptin-induced VM in breast cancer cells." (PMID 38791252, 2024). "Thus, AQP1 is involved in leptin-induced VM in breast cancer cells." (PMID 38791252, 2024). "Therefore, leptin and AQP1 are promising targets to inhibit VM in breast cancer cells." (PMID 38791252, 2024). "However, in breast cancer cells, AQP1 is mainly localized in the cellular cytoplasm." (PMID 36803413, 2023). "Therefore, targeting AQP1 offers promises in breast cancer treatment." (PMID 36803413, 2023). "In the present study, we discovered that the cytoplasmic AQP1 and GSK3β competitively interacted with the 12 armadillo repeats of β-catenin, a reaction that could inhibit the ubiquitin-proteasome degradation pathway of β-catenin in AQP1 overexpressed breast cancer cells." (PMID 32814878, 2021). "However, the role of RIPK1 in breast cancer oncogenesis and development remains one of the major unsolved issues, which may lead to a better understanding of AQP1-related TNBC cell death escape." (PMID 33980862, 2021).
breast cancer (continued). "The situation in MM, where higher levels of AQP1 are related to better prognosis is unlike that in other tumours, where increased levels of AQP1 are associated with poorer prognosis, including breast cancer, melanoma, urothelial carcinoma and pharyngeal squamous cell carcinomas." (PMID 27376267, 2016). "The potential mechanism by which AQP1 was involved in breast tumor growth and metastasis may be that AQP1 induced the development of angiogenesis by stimulating and activating endothelial cells through estrogen receptors in human breast cancer." (PMID 25886458, 2015). "In addition, AQP1 could facilitate cell migration in 4T1 breast cancer cells, AQP5 is required for proliferation and migration in MCF-7 breast cancer cells." (PMID 23468877, 2013). "Recently, AQP1, AQP3 and AQP5 overexpression was reported to disrupt cell polarity in breast cancer by interacting with the protein Scribble, leading to its downregulation." (PMID 39941100, 2025). "The contribution of AQP1, AQP3 and AQP5 to oxidative stress resistance has been investigated in colon and breast cancer cell lines by assessing their expression before and after treatment with H2O2." (PMID 39941100, 2025). "AQP1 and AQP5 overexpression plays a key role in cancer cell proliferation, migration, invasion, and chemosensitivity in several breast cancer subtypes." (PMID 39123442, 2024). "This preclinical study analyzed several aquaporins (AQP1, AQP3, AQP5) and their cellular arrangement after cryoablation in cultured breast cancer cells (MCF-7 and MDA-MB-231)." (PMID 38296892, 2024). "Moreover, leptin and AQP1 may be potential biomarkers in VM-related breast cancer." (PMID 38791252, 2024). "However, it remains unclear how cytoplasmic AQP1 effects breast cancer malignant progression." (PMID 36803413, 2023). "We found that AQP1 recruited ANXA2 to the Golgi apparatus, promoted Golgi apparatus extension, and induced secretion of ICAM1 and CTSS, which induced breast cancer cell invasion." (PMID 36803413, 2023). "Of note, we recently found that AQP1, AQP3 and AQP5 differentially affected the response of 3D-grown human breast cancer spheroids to conventional anticancer therapies." (PMID 37681917, 2023). "Collectively, these findings revealed that AQP1 interacted with ANXA2 to promote Golgi apparatus extension through F-actin, inducing breast cancer cell invasion." (PMID 36803413, 2023). "Correlation analysis using 194 IDC patients or the GEPIA database indicated that AQP1 was positively correlated with ANXA2, Rab1b, CTSS, and ICAM1 in breast cancer patients." (PMID 36803413, 2023). "AQP1 can also reside in the Golgi apparatus, where it can induce cell secretion of ICAM1 and CTSS, leading to the local invasion of breast cancer." (PMID 36803413, 2023). "Our results indicated that AQP1, ANXA2, and Rab1b formed a ternary complex in the Golgi apparatus to induce breast cancer local invasion." (PMID 36803413, 2023). "Co-immunoprecipitation, immunofluorescence assays and cell functional experiments were carried out to define the relationship among AQP1, ANXA2 and Rab1b and their re-localization in breast cancer cells." (PMID 36803413, 2023). "AQP1, AQP3, and AQP5 mRNA expression significantly increased in breast cancer tissue compared to normal tissue and localized to the cell membranes by immunohistochemistry." (PMID 36212456, 2022). "Actually, an aquaporin model has been previously proposed to explain the selectivity of CAP against cancer cells, where AQP1/3/5 were over-represented and AQP4 was under-expressed in breast cancers." (PMID 35637961, 2022). "The expression of AQP1, AQP3, and AQP5 has been found to be increased among resected breast cancer samples and carries a prognostic importance." (PMID 35847914, 2022). "For example, AQP1 is overexpressed in breast cancer and colorectal cancer, whereas AQP3 is upregulated in prostate and breast cancers." (PMID 33499000, 2021).
breast cancer (continued). "After implantation in target organs, breast cancer metastatic tumors induce formation of new blood vessels in response to both hypoxia-induced-factor-1 (HIF 1) and estrogen-activated AQP1 expression." (PMID 33499000, 2021). "In vitro data suggest that stable overexpression of AQP1 in MCF-7 (ER+ and PR+) and MDA-MB-231 (TNBC) breast cancer cell lines significantly increases cell invasion and proliferation." (PMID 30678106, 2019). "In a study where breast cancer cases were divided into two groups, HIF1-positive and HIF1-negative, in the HIF1-positive groups, the expression level of AQP1 was significantly higher than it was in the HIF1-negative group." (PMID 30555637, 2018). "Correlation of AQP1 and HIF1 expression in breast cancer tissues was demonstrated by Yin and colleagues." (PMID 28146084, 2017). "Hu and Verkman observed that AQP1 expression accelerated migration of mouse melanoma B16F10 and breast cancer 4T1 cell lines in vitro, with polarised expression of AQP1 observed at the leading edge of the migrating cells." (PMID 28146084, 2017). "Subsequent studies from our laboratory investigated expression of AQP1, the GLUT1 glucose transporter and Na, K-ATPase in canine mammary glands and mammary tumors." (PMID 24338153, 2014). "A recent study of human breast cancer showed that, among the 13 AQP members, only AQP1, AQP3, and AQP5 expression is elevated in breast cancer tissues relative to normal tissues." (PMID 23468877, 2013). "Similarly strong correlations between aquaporin expression and cellular proliferation have also been observed in other tumors (e.g., AQP1 in lung cancer 19 and AQP5 in breast cancer 20)." (PMID 40225573, 2025). "AQP1, AQP3, AQP4, AQP5, AQP7, and AQP9 expression were evaluated because these AQPs are expressed in breast tumors and have begun to be characterized as having roles in breast cancer progression and metastasis." (PMID 39123442, 2024). "Reports have shown that inhibition or overexpression of AQP1 has no significant impact on the proliferation of colon cancer cells and breast cancer cells." (PMID 38334883, 2024). "Estradiol upregulates AQP1 in prostate cancer; AQP2 in EC; and AQP3 in breast cancer." (PMID 37760476, 2023). "Besides, since endogenous AQP1 was undetectable in MDA-MB-231 and T47D cell lines, we further utilized two kinds of primary breast cancer cells to confirm the localization and function of AQP1." (PMID 36803413, 2023). "Our present study reported that AQP1 could promote Golgi apparatus extension, leading to increased cell secretion of ICAM1 and CTSS and increasing breast cancer cell migration and invasion." (PMID 36803413, 2023). "Furthermore, our present study discovered that AQP1 with ANXA2 and Rab1b formed a ternary complex in Golgi apparatus to induce breast cancer progression." (PMID 36803413, 2023). "Meta-analyses confirmed predominantly negative associations between AQP protein and RNA expression levels and patient survival times, most notably for AQP1 in lung, breast and prostate cancers; AQP3 in esophageal, liver and breast cancers; and AQP9 in liver cancer." (PMID 32679804, 2020). "There is a significant negative correlation between miR-3194-3p and AQP1 expression in 30 cases of breast cancer and adjacent tissues (r = −0.84, P < 0.01)." (PMID 32903818, 2020). "While AQP3 overexpression in early breast cancer patients was shown to be associated with a worse prognosis in patients with the HER2-overexpressing phenotype, AQP1 and AQP5 were reported as independent prognostic markers of survival for breast cancer patients." (PMID 31379986, 2019). "There is an increased expression of AQP1, AQP3, and AQP5 in breast cancer." (PMID 30555637, 2018). "Based on the correlations between AQP1 and HIF1 it is assumed that these proteins interact with each other and may regulate the oncogenesis of breast cancer." (PMID 30555637, 2018). "The expression of AQP1, AQP3, and AQP5 is up-regulated in breast cancer." (PMID 25886458, 2015).